RANBP2 (RAN binding protein 2)
Description:
E3 SUMO-protein ligase which facilitates SUMO1 and SUMO2 conjugation by UBE2I. Involved in transport factor (Ran-GTP, karyopherin)-mediated protein import via the F-G repeat-containing domain which acts as a docking site for substrates. Binds single-stranded RNA (in vitro). May bind DNA. Component of the nuclear export pathway. Specific docking site for the nuclear export factor exportin-1. Inhibits EIF4E-dependent mRNA export. Sumoylates PML at 'Lys-490' which is essential for the proper assembly of PML-NB. Recruits BICD2 to the nuclear envelope and cytoplasmic stacks of nuclear pore complex known as annulate lamellae during G2 phase of cell cycle. Probable inactive PPIase with no peptidyl-prolyl cis-trans isomerase activity.
Synonyms: NUP358; ADANE; ANE1; IIAE3; TRP1; TRP2
Tractability: Small molecule: a structure with a bound ligand is known. PROTAC: UniProt records ubiquitination sites on it; ubiquitination databases record sites on it; its protein half-life has been measured.
Target class: Enzyme; Transferase
Gene: Protein-coding gene on chromosome 2 (108,719,437 to 108,785,810, forward strand). Ensembl gene ENSG00000153201.
Subcellular location: Nucleus; Nucleus membrane; Nucleus, nuclear pore complex; Nucleus envelope
Subcellular location (Human Protein Atlas): Nuclear membrane; Cytosol; Nucleoplasm; Vesicles
Pathways (Reactome):
Disease: Defective TPR may confer susceptibility towards thyroid papillary carcinoma (TPC); HCMV Early Events; HCMV Late Events; NEP/NS2 Interacts with the Cellular Export Machinery; NS1 Mediated Effects on Host Pathways; Nuclear import of Rev protein; Rev-mediated nuclear export of HIV RNA; SARS-CoV-2 activates/modulates innate and adaptive immune responses; Signaling by ALK fusions and activated point mutants; Transport of Ribonucleoproteins into the Host Nucleus; Viral Messenger RNA Synthesis; Vpr-mediated nuclear import of PICs
Cell Cycle: Amplification of signal from unattached kinetochores via a MAD2 inhibitory signal; EML4 and NUDC in mitotic spindle formation; Mitotic Prometaphase; Nuclear Pore Complex (NPC) Disassembly; Resolution of Sister Chromatid Cohesion; Separation of Sister Chromatids
Metabolism of RNA: Transport of Mature mRNA Derived from an Intronless Transcript; Transport of Mature mRNA derived from an Intron-Containing Transcript; Transport of the SLBP Dependant Mature mRNA; Transport of the SLBP independent Mature mRNA; snRNP Assembly; tRNA processing in the nucleus
Metabolism of proteins: SUMOylation of DNA damage response and repair proteins; SUMOylation of DNA replication proteins; SUMOylation of RNA binding proteins; SUMOylation of SUMOylation proteins; SUMOylation of chromatin organization proteins; SUMOylation of ubiquitinylation proteins
Metabolism: IP3 and IP4 transport between cytosol and nucleus; IP6 and IP7 transport between cytosol and nucleus; IPs transport between nucleus and cytosol; Regulation of Glucokinase by Glucokinase Regulatory Protein
Cellular responses to stimuli: Regulation of HSF1-mediated heat shock response
Immune System: ISG15 antiviral mechanism
Signal Transduction: RHO GTPases Activate Formins
Gene Ontology:
Molecular function: peptidyl-prolyl cis-trans isomerase activity; protein binding; protein-macromolecule adaptor activity; small GTPase binding; SUMO ligase activity; SUMO transferase activity; kinase activator activity; protein-containing complex binding
Biological process: centrosome localization; negative regulation of transcription by RNA polymerase II; NLS-bearing protein import into nucleus; nuclear export; protein sumoylation; nucleocytoplasmic transport; protein folding; response to amphetamine
Cellular component: annulate lamellae; membrane; nuclear envelope; nuclear inclusion body; nuclear membrane; nuclear pore; nuclear pore cytoplasmic filaments; nuclear pore nuclear basket; nucleoplasm; nucleus; SUMO ligase complex; cytosol; cytoplasmic periphery of the nuclear pore complex
Genetic constraint (gnomAD): Loss-of-function variants: 56 observed, 302.29 expected, observed/expected ratio (o/e) 0.19, 90% interval 0.15 to 0.23. The upper end of that interval is the gene's LOEUF score, 0.23, which puts it in group 1 of 6, group 1 being the genes least tolerant of losing a copy. Missense variants: 3,113 observed, 3,756 expected, observed/expected ratio (o/e) 0.83, 90% interval 0.8 to 0.85. Synonymous variants: 1,156 observed, 1,292.6 expected, observed/expected ratio (o/e) 0.89, 90% interval 0.85 to 0.94.
Gene-disease validity (ClinGen):
ClinGen rates the evidence that RANBP2 causes each of these diseases.
familial acute necrotizing encephalopathy (autosomal dominant): Moderate. Familial acute necrotizing encephalopathy or ADANE is a potentially fatal neurological disease characterized by neuropathological lesions principally involving the brainstem, thalamus and putamen.
Leigh syndrome (autosomal dominant): Limited. A progressive neurological disease defined by specific neuropathological features associating brainstem and basal ganglia lesions.
Cancer hallmarks: genome instability and mutations (suppresses)
Homologues: Orthologues: macaque RANBP2 (97% identical), dog RANBP2 (90% identical), rat Ranbp2 (84% identical), pig RANBP2 (84% identical), mouse Ranbp2 (83% identical), guinea pig RANBP2 (80% identical), tropical clawed frog ranbp2 (51% identical), chimpanzee RANBP2 (14% identical), zebrafish ranbp1 (3% identical). Paralogues in human: RGPD4 (46% identical), RGPD8 (46% identical), RGPD5 (46% identical), RGPD6 (46% identical), RGPD3 (46% identical), RGPD1 (45% identical), RGPD2 (45% identical), RANBP3 (5% identical), RANBP3L (4% identical), RANBP1 (3% identical).
Diseases named in the same sentence as RANBP2 in open-access papers:
RANBP2 is named in the same sentence as 99 diseases in open-access papers, as found by Europe PMC text mining. Sharing a sentence is not in itself a finding about the gene and the disease. The quoted sentences say what the papers report.
viral infection (18 papers, 2006 to 2025). "It is possible that ANE1-associated mutations in RANBP2 alter the viral infection process by impacting the interactions between RanBP2 and either viral proteins or anti-viral host factors." (PMID 35408907, 2022). "Triggered by a febrile viral infection in a person with genetic susceptibility such as RANBP2 gene mutation (or less frequently, other similar gene mutation)." (PMID 36632547, 2022). "Despite this, the molecular mechanism by which RanBP2 mutations lead to the development of a cytokine storm after viral infection remains unclear." (PMID 38203469, 2023). "The nucleoporin Ran Binding Protein 2 (RanBP2) (also known as Nucleoporin 358 KDa, Nup358) has been implicated in a number of cellular processes, including host innate immune signaling pathways, and is known to influence viral infection." (PMID 38203469, 2023). "This modulation may be disrupted by ANE1 mutations in RanBP2, resulting in cytokine storms upon viral infections." (PMID 38203469, 2023). "However, how RanBP2 mutations promote the development of a cytokine storm in response to viral infection remains elusive." (PMID 35408907, 2022). "Therefore, one speculative explanation is that mutations in RanBP2 cause mitochondrial metabolic disorders in response to viral infection." (PMID 35408907, 2022). "Yet, haploinsufficiency of RanBP2 (this work) and Nup96 predominantly produce, instead, CNS-restricted deficits in energy metabolism and alterations in the immune system linked to the down-regulation of interferon-β-regulated proteins and increased susceptibility of viral infection, respectively." (PMID 17069463, 2006). "This multifaceted involvement of RANBP2 in various stages of viral infection underscores its significance as a key mediator in the intricate interplay between viruses and host cells." (PMID 40271196, 2025). "Numerous investigations underscore the pivotal role of RANBP2 in viral infections, wherein RANBP2 exhibits the capacity to actively facilitate the nuclear entry or exit of nuclear viruses." (PMID 40271196, 2025). "In conclusion, our study reveals that STAT1 is a sumoylation substrate of RanBP2, and that RanBP2 facilitates viral infection by attenuating interferon-α-induced antiviral innate immunity, likely by sumoylating STAT1." (PMID 38203469, 2023). "This review summarizes recent advances in our understanding of how mutations in RANBP2 contribute to ANE1 and discusses how RanBP2 interacts with distinct viruses and affects viral infection." (PMID 35408907, 2022). "Answers regarding the role of host mutations in RANBP2, a nuclear pore protein, involved in the pathogenesis of recurrent ANE1 makes this condition a very good model for understanding the links between genetics, viral infections and neuroinflammation." (PMID 35356001, 2022). "As a defense against viral infection, USP9x reduces the interaction between pIIIa and RANBP2, resulting in decreased viral propagation." (PMID 35709296, 2022). "In November 2021, a number of clinicians and basic scientists presented their work on this disease and on the interactions between RanBP2/Nup358, viral infections, the innate immune response and other cellular processes." (PMID 35485383, 2022). "Mounting evidence has shown that RanBP2 interacts with distinct viruses to regulate viral infection." (PMID 35408907, 2022). "Five separate missense mutations in RanBP2 cause acute necrotizing encephalopathy 1 (ANE1), which manifests as a sharp rise in cytokine production after common viral infections such as influenza and parainfluenza." (PMID 33600493, 2021). "Second, the role of RanBP2 in antiviral innate immunity may vary depending on different viral infections or various stages of viral infection." (PMID 38203469, 2023). "We observed that the efficiency of HSV-1-GFP infection was comparable between Ctrl and RanBP2-dE3-3 Vero cells, confirming that RanBP2 might only affect viral infection by interfering with antiviral innate immunity." (PMID 38203469, 2023).
viral infection (continued). "Further investigation is needed to determine whether RanBP2 regulates cytokine production through additional means, such as interacting with the antiviral innate immune response after viral infection." (PMID 38203469, 2023). "Mutations in RanBP2 are associated with acute-necrotizing encephalopathy type 1 (ANE1), a pediatric neurological disease that manifests as an overproduction of cytokines (known as a “cytokine storm”) after viral infection." (PMID 35408907, 2022). "Dominant missense mutations in RanBP2/Nup358 cause Acute Necrotizing Encephalopathy (ANE), a pediatric disease where seemingly healthy individuals develop a cytokine storm that is restricted to the central nervous system in response to viral infection." (PMID 35485383, 2022). "As detailed above, RanBP2 interacts with different viruses and plays a role in viral infection." (PMID 35408907, 2022). "Finally, RANBP2 could be a promising therapeutic target in some genetic forms of ANE, suppressing the cytokine storm and the hyperinflammation associated with viral infection." (PMID 40757726, 2024). "Increasing evidence demonstrated that RANBP2 may interact with viruses to regulate viral infection." (PMID 40757726, 2024). "Mutations in the RANBP2 gene are associated with acute necrotizing encephalopathy type 1 (ANE1), a rare condition where patients experience a sharp rise in cytokine production in response to viral infection and undergo hyperinflammation, seizures, coma, and a high rate of mortality." (PMID 35408907, 2022). "We find that this domain affects viral infection, nucleoporin requirements, MX2 sensitivity, and integration targeting in a CA-specific manner, providing detailed insights into how RANBP2 contributes to HIV-1 infection." (PMID 39853118, 2025). "It has been observed that the C-terminal cyclophilin domain (Cyp) of RanBP2 interacts with the Cyclophilin A (CypA) binding loop of HIV-1 capsid (CA), and this interaction facilitates the nuclear import of HIV-1 PIC and viral infection." (PMID 35408907, 2022). "In order to investigate the role of RanBP2 in HIV-1 replication, we performed RNAi studies on Magi cells, a Hela cell line that expresses CD4, CCR5, and CXCR4 receptors, followed by the viral infection." (PMID 21179483, 2010). "Upon artificial induction of pIIIa expression as well as during natural virus infection, the ubiquitin-proteasome system’s inhibition had no impact on viral protein pIIIa or RANBP2 steady state concentrations." (PMID 35709296, 2022). "Recent findings indicate that RanBP2 might be an important therapeutic target, not only in the suppression of ANE1-driven cytokine storms, but also to combat hyperinflammation in response to viral infections." (PMID 35408907, 2022). "To rule out any inhibitory effect of RanBP2 siRNA on viral reverse transcription, we further examined the levels of viral late reverse transcription products 12 hrs after the virus infection that would reflect the total viral DNA synthesized in RanBP2 depleted cells and the controls." (PMID 21179483, 2010). "To further verify whether RanBP2 affects HSV-1 infection by other mechanisms aside from regulating the antiviral innate immunity, we also generated RanBP2 mutant cells (RanBP2-dE3-3) in Vero cell lines, which are incapable of inducing type I interferon upon viral infection." (PMID 38203469, 2023).
cervical carcinoma (14 papers, 2019 to 2025). A carcinoma arising from either the exocervical squamous epithelium or the endocervical glandular epithelium. "In cervical cancer cells, YTHDF1 modulation of RANBP2 translation in an m6A‐dependent manner enhances cell growth, migration and invasion, making it a critical target for cervical cancer therapy." (PMID 39135292, 2024). "Additional studies have analyzed RIP-seq, meRIP-seq, and ribosome profiling sequencing (Ribo-seq) data after YTHDF1 knock-down and found that RAN Binding Protein 2 (RANBP2) is a key target of YTHDF1 in cervical cancer cells." (PMID 39342406, 2024). "At the same time, knockdown of RANBP2 reversed the effect of overexpression of YTHDF1 on cervical cancer progression, indicating that YTHDF1 promotes cervical cancer progression by regulating RANBP2 expression in an m6A-dependent manner." (PMID 35707365, 2022). "Combined with on-line data analysis, RANBP2 is identified as the key target of YTHDF1 in cervical cancer cells." (PMID 33816306, 2021). "Together, our study demonstrates the oncogenic role of YTHDF1 in cervical cancer by regulating the expression of RANBP2." (PMID 33816306, 2021). "CCK-8 assays showed that the proliferation of Hela and Siha cervical cancer cells was inhibited after RANBP2 knockdown." (PMID 33816306, 2021). "In conclusion, our study showed that the m6A “reader” YTHDF1 promotes the proliferation, migration and invasion of cervical cancer cells, and we also identified RANBP2 as the direct target of YTHDF1." (PMID 33816306, 2021). "In this study, YTHDF1 mediates the up-regulation of RANBP2 in an m6A-dependent manner in cervical cancer." (PMID 33816306, 2021). "Through combined on-line data analysis of RIP-seq, meRIP-seq and Ribo-seq upon YTHDF1 knockdown, RANBP2 was identified as the key target of YTHDF1 in cervical cancer cells." (PMID 33816306, 2021). "YTHDF1 regulated RANBP2 translation in an m6A-dependent manner, which plays an important role in cervical cancer." (PMID 33816306, 2021). "To further examine the role of RANBP2 in cervical cancer cells, we designed two shRNAs targeting RANBP2." (PMID 33816306, 2021). "NUSAP1 overexpression induced SUMOylation of TCF4 via binding NPC protein, RanBP2, is involved in the process of cervical cancer metastasis and progression." (PMID 30678687, 2019). "Mechanistically, upregulation of NUSAP1 induced SUMOylation of TCF4 via interacting with SUMO E3 ligase Ran-binding protein 2 (RanBP2) and hyperactivated Wnt/β-catenin signaling in cervical cancer cells." (PMID 30678687, 2019). "Moreover, the oncogenic role of YTHDF1 was observed to influence the upregulation of RANBP2 mRNA and enhance the progression of cervical cancer in an m6A-dependent manner." (PMID 37259333, 2023). "YTHDF1 aggravates cervical cancer progression through m6A-mediated RANBP2 upregulation." (PMID 34677810, 2021). "RANBP2 potentiated the growth, migration and invasion of cervical cancer cells." (PMID 33816306, 2021). "In our study, RANBP2 promoted the growth, migration and invasion of cervical cancer cells." (PMID 33816306, 2021). "In addition, IHC results revealed that RANBP2 expression was higher in cervical cancer tissues compared to normal tissues." (PMID 33816306, 2021). "We tested whether SUMOylation E3 ligase (RanBP2) co-IPed with endogenous NUSAP1 in cervical cancer cells." (PMID 30678687, 2019). "Furthermore, the colony formation ability and proliferation of YTHDF1-overexpressing Hela and Siha cells were significantly increased, whereas knockdown of RANBP2 could compromise the effect of YTHDF1 overexpression on cervical cancer cells." (PMID 33816306, 2021). "Specifically, the up-regulation of RANBP2 expression induced by YTHDF1 potentially augments RAN-GTPase activity, thereby exacerbating the progression of cervical cancer." (PMID 40271196, 2025). "The correlation analysis suggested that there was a positive correlation between the protein expression of RANBP2 and YTHDF1 in cervical cancer." (PMID 33816306, 2021).
cervical carcinoma (continued). "For instance, in cervical cancer, NUSAP1 is shown to bound to the SUMO-E3 ligase Ran binding protein 2 (RanBP2) to induce the sumoylation of TCF4, thereby enhancing the Wnt/β signaling pathway and inducing tumor metastasis." (PMID 33927744, 2021). "Our study demonstrated the oncogenic role of YTHDF1 in cervical cancer by regulating RANBP2 expression and YTHDF1 represents a potential target for cervical cancer therapy." (PMID 33816306, 2021). "Our results also reveal that NUSAP1 increased the nuclear import of the TCF4 and β-catenin and their transcriptional activity via interacting with RanBP2 protein, and then enhanced CSCs properties and EMT processes in cervical cancer." (PMID 30678687, 2019). "YTHDF1 regulates the translation of RANBP2 in an m6A-dependent manner, but not its mRNA expression, thereby affecting cervical cancer cell growth, migration, and invasion." (PMID 39342406, 2024). "YTHDF1 regulated the translation of RANBP2, which potentiated the growth, migration, and invasion of cervical cancer cells in an m6A-dependent manner without any effect on its mRNA expression." (PMID 36058934, 2022). "RANBP2 expression up-regulated by YTHDF1 might enhance the activity of RAN GTPase activity and aggravate the progress of cervical cancer, which might need more investigations in further study." (PMID 33816306, 2021). "The increased sample size enabled identification of SMGs previously unreported in cervical carcinoma including NBPF10 (8%), RANBP2 (6%), MSN (6%), KRT8 (6%), POTEC (6%), ZC3H11A (4%), BMS1 (4%), GPX1 (3%), OTOP1 (3%), DNAH12 (2%), COIL (2%), TBC1D26 (2%), SPRED3 (2%), FAM115A (2%), and ARIH1 (1%)." (PMID 34620846, 2021). "Studies also showed that the over-expression of NUSAP1 stimulated sumoylation of TCF4 via interacting with SUMO E3 ligase Ran-binding protein 2 and hyperactivated Wnt/β-caternin signaling to induce cancer stem cell properties and EMT, and finally promoted the metastasis of cervical cancer." (PMID 31729978, 2019). "Moreover, NUSAP1 induced SUMOylation of TCF4 via interacting with SUMO E3 ligase Ran-binding protein 2 (RanBP2) and potently activated the Wnt/β-catenin signaling pathway, thus contributing to the metastatic and CSC-likeproperties of cervical cancer cells." (PMID 30678687, 2019).